OR5A1 (olfactory receptor family 5 subfamily A member 1)
Description:
Odorant receptor.
Synonyms: OR5A1P; OST181; OR11-249
Tractability: Antibody: UniProt places it where antibodies can reach, with medium confidence; UniProt predicts a signal peptide or a membrane-spanning region; its Gene Ontology location is reachable by antibodies, with medium confidence.
Gene: Protein-coding gene on chromosome 11 (59,436,469 to 59,451,380, forward strand). Ensembl gene ENSG00000172320.
Subcellular location: Cell membrane
Pathways (Reactome):
Sensory Perception: Expression and translocation of olfactory receptors
Gene Ontology:
Molecular function: odorant binding; olfactory receptor activity; G protein-coupled receptor activity
Biological process: sensory perception of smell; detection of chemical stimulus involved in sensory perception of smell; G protein-coupled receptor signaling pathway
Cellular component: plasma membrane; membrane
Genetic constraint (gnomAD): Loss-of-function variants: 15 observed, 20.08 expected, observed/expected ratio (o/e) 0.75, 90% interval 0.5 to 1.15. The upper end of that interval is the gene's LOEUF score, 1.15, which puts it in group 5 of 6, group 1 being the genes least tolerant of losing a copy. Missense variants: 378 observed, 401.3 expected, observed/expected ratio (o/e) 0.94, 90% interval 0.87 to 1.03. Synonymous variants: 169 observed, 162.67 expected, observed/expected ratio (o/e) 1.04, 90% interval 0.92 to 1.18.
Homologues: Orthologues: chimpanzee OR5A1 (99% identical), macaque OR5A1 (97% identical), dog OR5A1 (87% identical), rabbit OR5A1 (87% identical), mouse Or5a1 (84% identical), rat Or5a1 (82% identical), tropical clawed frog or5f1l1.3 (48% identical), tropical clawed frog or5f1l1.1 (47% identical), tropical clawed frog or5f1l1.2 (46% identical), tropical clawed frog or8a1 (44% identical). Paralogues in human: OR5A2 (65% identical), OR5AN1 (57% identical), OR5B21 (53% identical), OR8I2 (52% identical), OR5B12 (52% identical), OR5I1 (52% identical), OR5W2 (52% identical), OR5AP2 (51% identical), OR5AU1 (51% identical), OR8U1 (51% identical), OR9G4 (50% identical), OR8H1 (50% identical), and 84 more.
Diseases named in the same sentence as OR5A1 in open-access papers:
OR5A1 is named in the same sentence as 2 diseases in open-access papers, as found by Europe PMC text mining. Sharing a sentence is not in itself a finding about the gene and the disease.
OR5A1 shares sentences with these, for which no sentence is quoted: diabetes (1 paper); entropion (1).